EPCAM (epithelial cell adhesion molecule)
Diseases named in the same sentence as EPCAM in open-access papers (continued):
Sharing a sentence is not in itself a finding about the gene and the disease.
tumor (continued). "Nevertheless, in the following years, it became clear that higher numbers of CTC can be detected using alternative, EpCAM-independent methods, suggesting that a mixture of EpCAM-positive and EpCAM-negative tumor cells circulates in the blood." (PMID 31636732, 2019). "FACS analysis using anti-mouse immunoglobulin revealed that the therapeutic CD47 mAb had effectively bound on the surface of CD45− EpCAM+ tumor cells (data not shown)." (PMID 30938231, 2019). "Because use of IV anti-EpCAM immunotoxin did not result in tumor regressions in a separate study, we suggest that anti-tumor immunity is more likely to explain regressions of un-injected tumors in this study." (PMID 30621280, 2019). "Finally, EPCAM-targeted CAR-T cells have been generated using genetically modified T cells that express a chimeric antigen receptor (CAR), and that bind to tumour cells expressing the EPCAM protein on the cell surface." (PMID 31426611, 2019). "Positive cells were tumor cells, as revealed by anti-CEA and anti-EpCAM staining." (PMID 31752131, 2019). "Indeed, detection of CTCs by EpCAM/DAPI-positive selection and CD45-negative staining identified CTC clusters for 50 (primary disease) to 67% (recurrent tumor) of the 54 patients explored, with a correlation to platinum-resistance." (PMID 31167492, 2019). "Therefore, we assessed whether correlation with worse PS (and thus greater tumour load) could be found with different levels of those exosomal proteins resulted to stratify patients in different clusters after hierarchical cluster analysis: EpCAM, CXCR4, CD81 and CD9." (PMID 31048929, 2019). "We found that depletion of SHCBP1 remarkably repressed the cellular stemness enhancement caused by EGF stimulation, as revealed by reduced EGF-promoted formation of tumor spheres, expression of stem cell markers, and CD44/EpCAM double-positive as well as SP fraction." (PMID 30177836, 2019). "Immunofluorescence staining results demonstrate that the increase of EpCAM+ CD4+ T cells is also observed in tumor tissues, rather than para-cancerous tissues." (PMID 31354723, 2019). "In prostate cancer and NSCLC tumor models, CAR T-cells targeted against EpCAM and EGFR antigens could successfully eradicate CSCs and cancer cells." (PMID 31709180, 2019). "Moreover, tumor sphere cells expressed higher CD49f and lower ASMA than parental cells, while both parental cells and tumor sphere cells were EpCAM+TP63-." (PMID 31196164, 2019). "Besides, the definition of CTCs was not quite the same between Microsieve and Cellsearch; Microsieve classified CK+, CD45- nucleated cells as canonical CTCs, while Cellsearch classified EpCAM+, CK+, DAPI+, and CD45- nucleated cells as tumor cells." (PMID 31729954, 2019). "Specific HCC tumor markers, such as CK19, Sox9, and EpCAM, were expressed in all analyzed passages." (PMID 31726709, 2019). "We investigated the expression of the typical epithelial cell adhesion molecule N‐cadherin and E‐cadherin and mesenchymal marker vimentin to determine whether EMT occurs during tumor growth and compared the results with RGS5 expression at the same sites." (PMID 31049219, 2019). "The levels of EpCAM were observed to be low in 10 of 39 (26%) of breast cell lines, which is consistent with results showing EpCAM alone does not offer a broad detection of tumor cells." (PMID 31581693, 2019). "In Pt #19 tumor, both CD45+ hematopoietic cells and EpCAM+ EOC expressed MHC class II (HLA-DR)." (PMID 31221207, 2019). "We reveal excessively activated pp38 MAPK-pMAPKAPK2 signaling expressed by EpCAM+ CD4+ T cells in tumor tissues in CC patients, indicating that the p38 MAPK pathway might be a potential therapeutic target in EpCAM+ CD4+ T cell-rich CC patients." (PMID 31354723, 2019). "It should be noted that EpCAM was observed on almost all tumor cell surfaces and no significant alteration of the EpCAM signal was observed in our serially transplanted PDXs." (PMID 31126020, 2019).
tumor (continued). "Overall, numerous studies have provided evidence that CTC expressing no or low EpCAM are frequently detected in specific tumor types and an increasing number of studies have demonstrated that EpCAM-negative CTC are associated to worse prognosis." (PMID 31636732, 2019). "Multivariate confirmed the prognostic value of HR(−)/TWIST1(+) and TWIST1(+)/N2-3, in the EpCAM(+) CTC fraction for the prediction of DFI independently from patients’ age, tumor T stage, grade, nodal status alone and the HR, and HER2 status of the primary tumor." (PMID 31261917, 2019). "The isolation by size of epithelial tumour cells method (ISET,) might be a good alternative for CTC detection, as it is unbiased by the needed presence of cell surface EpCAM." (PMID 31248203, 2019). "In vitro, MT110 exhibited a potent activity in killing EpCAM-overexpressing tumor cells by redirected unstimulated human peripheral T cells (CD4+ and CD8+).16, 62 MT110 was efficacious in three in vivo models (tumor growth inhibition and elimination of established tumors)." (PMID 31011631, 2019). "IHC analysis also demonstrates a heterogeneous loss of epithelial markers, including epithelial cell adhesion molecule (EpCAM) or Keratin 76 (Krt76), in clinical specimens of HNSCC or oral SCCs, respectively, leading to more aggressive tumor progression and altered immune landscape." (PMID 31024913, 2019). "The frequencies of a single marker expression were 10.4% (DLK1), 6.8% (EpCAM), 4.0% (NCAM), and 2.4% (CK19), indicating that other HPC marker-positive HCCs (approximately 33.7% of the total number of HPC marker-positive tumours) expressed two or more HPC proteins." (PMID 29774107, 2018). "Silencing of the PPAR-α and CD36 genes significantly attenuated the FFA induced EpCAM, β-catenin and cyclinD1, further confirmed that FFA and FGF15/FGFR4 signaling could play a critical role in contributing to tumor-initiation and the development of HCC." (PMID 29973237, 2018). "We isolated 956 EpCAM+ cells and observed 762 negative, 139 low, and 55 high HIF1α protein-positive cells from the tumor." (PMID 30389926, 2018). "In the present study, we investigate the clinical relevance of both EpCAM+ CK+ CD45- tumor microparticles without a nucleus in blood, defined here as tumor-derived Extracellular Vesicles (tdEVs) and soluble cytokeratins in plasma of CRCP patients." (PMID 29721202, 2018). "EpCAM (epithelial cell adhesion molecule; CD326 (cluster of differentiation 326)) was originally identified as a novel tumour-specific cell surface antigen after immunisation of mice with cancer cells in 1970s, and was later defined as a cell–cell adhesion molecule." (PMID 29305578, 2018). "While there have been a number of missteps, with high affinity antibodies or the lack of stratification of patients based on EpCAM tumour expression, there have now been some very successful trials in small cohorts of patients." (PMID 29329202, 2018). "The circulating tumor cells in these patients have been defined as cells co-expressing EpCAM and cytoketarins (8, 18 and 19), without expression of the CD45 hematopoietic marker." (PMID 30060526, 2018). "The LN-229 (mHsp70: 80 ± 4%), U-87 (mHsp70: 96 ± 4%) brain, and MIA PaCa-2 (mHsp70: 97 ± 3%) pancreas tumor cells are only positive for mHsp70, but negative for EpCAM." (PMID 30443493, 2018). "This population may come from the BM and/or the tumor (GFP+/EpCAM+), or from GFP−/EpCAM+ populations from various organs including the GFP−/EpCAM+ population in the tumor." (PMID 30546048, 2018). "We demonstrated that KD of EpCAM prolonged the survival of tumour-bearing mice with and without chemo−/radiotherapy, suggesting that expression of EpCAM is associated with unfavourable prognosis in CaP." (PMID 30419852, 2018). "EpCAM specific CAR T cells have been developed to treat prostate, breast, and peritoneal cancers and have shown suppressed tumor progression/delayed disease as well as CAR T cell trafficking into the tumor site." (PMID 30031396, 2018).
tumor (continued). "With a low affinity, edrecolomab bound only to cells with high expression, but due to the heterogeneity of tumours, not all of the tumour cells overexpressed EpCAM to the extent that the antibody theoretically bound to them." (PMID 29329202, 2018). "Overall, the ratio of PC-3-EpCAM-KD tumour volumes decreased faster in response to DTX compared to the VC group (P < 0.05), suggesting that the KD of EpCAM can increase the chemosensitivity of CaP tumours in orthotopic mouse model." (PMID 30419852, 2018). "Furthermore, EpCAM+MHCII− cells were able to generate, when injected in immunodeficient mice, tumor heterogeneity." (PMID 30060526, 2018). "Assuming the artificial mixture of immune and tumor cells defines TF motif accessibility characteristic for these cell types, we compared TF motif variability of 4T1 with splenocytes, and of CD45+ tumor-infiltrating immune cells to EpCAM+ primary tumor cells." (PMID 30389926, 2018). "Future studies could explore other products secreted into the tumor stroma like metalloproteases or TGFβ, or cell surface products expressed on tumor cells like Her2, PSMA, EpCAM, or nucleolin." (PMID 30135425, 2018). "Importantly, increased EPCAM and pluripotency gene expression was quantified by RT-PCR in a cohort of HBV-related HCCs that exhibited poor prognosis after tumor resection." (PMID 29498629, 2018). "HCC samples were considered positive for each HPC marker if more than 5% of tumour cells in a single section were stained; as a result, 18.3%, 7.1%, 14.3%, and 8.0% patients were found to have high levels of DLK1, NCAM, EpCAM, and CK19 in tumours, respectively." (PMID 29774107, 2018). "The presence of tumor cells regardless of tumor-associated antibody expression was considered as CTC, and the total number of CTCs in entire three slides (CK, EpCAM and CD10) was counted." (PMID 30315187, 2018). "We found that the mRNA expression of ISGF3 subunits in the TCGA dataset comes predominantly from immune cells as opposed to tumor cells (surrogated by EPCAM and E cadherin)." (PMID 30355451, 2018). "Similarly, si-hVDAC1 treatment of A549-derived tumours greatly decreased the expression of ABCG2, SOX2, CD44, CD144, CD133, KLF4, Oct3/4, EPCAM and Nanog, also as evaluated by IHC, immunoblotting or q-RT-PCR." (PMID 30544833, 2018). "Next, we found that ADM in tumor tissues was significantly increased when compared to that in non-tumor tissues, and that a positive correlation between mast cell degranulation and ADM production most likely derived from EpCam+ tumor cells within GC tumors." (PMID 30305610, 2018). "Immunohistochemical staining of 31 prechemotherapy tumor specimens showed positive membranous EpCAM staining in 25 (80.65%) specimens and negative in 6 (19.35%)." (PMID 28851352, 2017). "Treatment of the samples with free EpCAM BiTE and the EpCAM BiTE‐expressing viruses led to strong T‐cell activation (measured by CD25 expression), and a depletion of EpCAM‐positive tumour cells to background levels, although FAP‐positive (EpCAM‐negative) fibroblasts showed no change in numbers." (PMID 28634161, 2017). "The tumor showed positive immunostaining for Vimentin, CD31, CK7, D2–40, c-MYC, Ki67, focal positivity for PanCK, and negative immunostaining for Factor VIII, CD34, WT1, CK5/6, Calretinin, EMA, HBME-1, CEA, p63, EpCAM, Bcl-2, TTF1 and Thyroglobulin." (PMID 28810922, 2017). "So far, all clinical trials reported herein did not specifically deal with the eradication of Tumor Infiltrating Cells (TICs) in particular, but rather with the treatment of EpCAM-positive cancers." (PMID 28531111, 2017). "The degree of K19 and EpCAM expression was well correlated with tumor stromal FAP expression (P = 0.042 and P = 0.004, respectively), and the degree of CD133 expression was well correlated with tumor stromal α-SMA expression (P = 0.005)." (PMID 29245907, 2017).
tumor (continued). "While ALDH+/EpCAM+ cells expressing scramble shRNA (PS1-ALDH+/Scrsh) rapidly formed large tumours in vivo, ALDH+/EpCAM+ cells expressing ABshRNA-1 (PS1-ALDH+ /ABsh-1 cells) only formed small tumours or could not form tumour at all." (PMID 28440295, 2017). "After a 4-hour perfusion of antibody solution of both EpCAM and CD44, the antibodies could be seen throughout the FNAB tumor sample." (PMID 28085924, 2017). "To elucidate the role of EpCAM in MSC migration, we examine the abilities of MSC to migrate towards NOD/SCID mice that have been serially transplanted with EpCAMhigh versus EpCAMlow tumor xenografts." (PMID 28903370, 2017). "Since EpCAM and CKs are also expressed by circulating epithelial non-tumor cells, thus they are not CTC-specific and can lead to false positives." (PMID 27738343, 2017). "Compared to non-NPC, NPC specimens had increased expression of EPCAM, of which tumours from advanced stage of NPC had higher expression." (PMID 28959019, 2017). "CTC load directly assessed either by CTC count or by considering EPCAM concentrations as surrogate marker did not appear to reflect tumour burden." (PMID 28321147, 2017). "Ep+NSCs did not generate any tumor even with 50,000 cells/mice whereas EpCAM‐ HCC cells formed a very small tumor in one out of three mice injected with 50,000 cells." (PMID 28176469, 2017). "CSCs expressing high levels of EpCAM can adapt to the hypo-nutrient tumor microenvironment better than non-CSCs that express low levels of EpCAM." (PMID 28279189, 2017). "One of the reasons would be that the CellSearch system depends on EpCAM expression for capturing the tumor cells, which is not necessarily expressed by all CTCs." (PMID 28640869, 2017). "In conclusion, EpCAM shows high tumor distinctiveness, because of the absence of staining in LNs without metastases." (PMID 28820475, 2017). "Intriguingly, PAR-1 expression did not correlate to epithelial (tumor) cell markers Epithelial cell adhesion molecule (EpCAM), Cadherin 1 (CDH1) and Mucin 1 (MUC1)." (PMID 28173772, 2017). "As our MCA system is not dependent on EpCAM expression for tumor cell enrichment, it potentially allows us to detect CTCs of cancer types with low and negative EpCAM expression." (PMID 28640869, 2017). "While the EpCAM based approach failed to successfully isolate tumor cells, CD45 based approaches showed intermediate recovery rates." (PMID 29152114, 2017). "Sox9 was most readily expressed in the tumor nodules the cohort, followed by CK19 and then EpCAM." (PMID 28764740, 2017). "In the capture efficiency tests, the device has exhibited a high capture efficiency in detecting either EpCAM positive (MCF-7, A549, SW480), or EpCAM negative cells (Hela), range from 80.3 to 88% in detecting tumor cells from DMEM." (PMID 27935872, 2017). "An increased grafting rate for tumours derived from patients with worse outcome (p = 0.006), higher stage (p = 0.038) and higher CD133+/CXCR4+/EpCAM− stem cell content (p = 0.019) was observed whereas a trend towards an association with SUVmax higher than 8 (p = 0.084) was detected." (PMID 28751748, 2017). "Exposure of CD3 cells to the EpCAM BiTE in the absence of tumour cells gave a very modest increase in CD69 and CD25, and this indicates that antibody‐mediated clustering of CD3 is essential for full activation by this anti‐CD3 binding." (PMID 28634161, 2017). "Moreover, PDX take rate correlated with patient OS and DFS, tumour stage, SUV, and presence of CD133+/CXCR4+/EpCAM− cells, consistent with more aggressive tumours prone to disseminate." (PMID 28751748, 2017). "Numerous technologies relying on positive selection of CTCs utilize antibodies against EpCAM, a cell surface glycoprotein expressed on tumor cells of epithelial lineage, but not on leukocytes." (PMID 28544498, 2017). "In cell fractions of CD133+ and CD133−/EpCAM+ cells we detected a deletion at chromosome 19p that was not evident in corresponding tumour tissue." (PMID 28347289, 2017).
tumor (continued). "So far, the development of targeted therapies was mostly fueled by knowledge related to primary tumor biology and, currently, around one dozen therapeutic antibodies and 28 different inhibitors are in clinical application, targeting essentially the tumor antigens HER2, EGFR, EpCAM, BRAF and VEGF." (PMID 27683128, 2017). "Our results show that this assessment methodology can more accurately determine CTC numbers to quantify circulating tumor cells, including EpCAM-negative CTCs, in patients with solid tumors, as well as identify CTCs in patients with hematological malignancies." (PMID 27206795, 2016). "It was concluded that this discrepancy was not due to an intrinsic characteristic of the primary tumor, but most probably to EpCAM knockdown and/or EMT induction." (PMID 27527155, 2016). "Furthermore, fluorescence immunohistochemistry experiments confirmed that our constructs can distinguish between healthy and TNBC tumor tissues, because the latter express high levels of EGFR, EpCAM or CSPG4." (PMID 27448975, 2016). "Nevertheless, the antigen combination of EpCAM and CD147, successfully detected in vivo derived CD147+EpCAM+ taMPs and their median values significantly increased in cancer patients by an average of 4.8 fold across all investigated tumour entities." (PMID 27127176, 2016). "Another approach is to use CD146 to detect EpCAM-negative tumor cells and CD49f for the detection of CK-negative cells, improving detection rates." (PMID 27529216, 2016). "Although EpCAM staining was detectable in all aCP tumour samples, no specific immunoreaction was visible in the group of pCP." (PMID 27431859, 2016). "In this report, we showed that CTCs isolated by the EpCAM-based method had complex and diverse genetic features that were similar to those of tumor samples in some, but not all, cases." (PMID 27892470, 2016). "Similarly to CD44+/hi phenotypes, sorted FGFR+/hi cells had larger volumes, formed more tumor spheres, grew faster in vivo with bigger tumor mass, and expressed more CD44, EpCAM, and HER2." (PMID 27107424, 2016). "EpCAM+ and EpCAM+CD147+ taMPs might serve as an early indicator of cancer growth and monitor successful anti-tumour therapy and might be used as important liquid biopsy tool to differentiate between therapy responders and therapy non-responders." (PMID 27127176, 2016). "Taken together, our results indicate that TINCR is a tumour suppressor that, when downregulated, may promote CRC growth and metastasis, and accelerate hydrolysis of EpCAM." (PMID 27009809, 2016). "On the contrary, EpCAM and EGFR were found to be expressed at high rates (high percentage) and with moderate to high Median Fluorescence Intensity (MFI) in most of the analysed tumour cell lines." (PMID 27711186, 2016). "Cells undergoing EMT and poorly differentiated stem cell-like tumor cells are likely EpCAM negative." (PMID 26695546, 2016). "The expression of EpCAM in brain metastases was similar to that of the primary tumours, indicating that EpCAM does not seem to be permanently downregulated in metastases to a larger extent." (PMID 27302574, 2016). "While taMPs could aid in of the detection of the investigated tumour entities, the questions remained if taMPs, EpCAM+ taMPs and especially EpCAM+CD147+ taMPs could reflect tumour burden." (PMID 27127176, 2016). "We next screened by flow cytometry this panel of cell tumour phenotypes with epithelial markers (EpCAM, E-cadherin, Muc1, claudin-3 andclaudin-4) or non-epithelial markers (N-cadherin, vimentin, CD66, EGFR, FGFR, EphB4,ALDH1 and CD49f)." (PMID 27711186, 2016). "Previous studies have shown that CD90, EpCAM, CD133, CD24, OV-6 and CD44 can be used as CSC markers in HCC, and cells expressing these markers possessed CSC characteristics such as self-renewal, tumor generation and aggressive growth." (PMID 27835990, 2016).